HMGB1 (high mobility group box 1)
Diseases named in the same sentence as HMGB1 in open-access papers (continued):
Sharing a sentence is not in itself a finding about the gene and the disease.
ischemic stroke (continued). "In conclusion, our data revealed that AA9 improved brain infarct size and neurological deficits in the mice model of MCAO, and it also inhibits ischemic stroke‐induced neuronal damage, by rescuing iron deposition, ROS accumulation, and GPX4, Nrf2, HO‐1, HMGB1, and NF‐κB p65 expression." (PMID 36852441, 2023). "The numbers of HMGB1+ neurons were similar in STAT1 mKO mice and WT mice 24 h after MCAO, suggesting similar neuronal injury and the initial trigger of proinflammatory responses at the acute stage after ischemic stroke." (PMID 37516843, 2023). "As plasma HMGB1 and NET levels were decreased, we next examined whether thrombocytopenic mice were protected from ischemic stroke brain injury." (PMID 35358095, 2022). "In an animal model of ischemic stroke, RAGE expressed on microglia can mediate HMGB1 neurotoxicity." (PMID 36483598, 2022). "Therefore, the inhibition of cytoplasmic translocation of HMGB1 and TLR4 signal becomes a potential strategy treating the ischaemic stroke." (PMID 34231932, 2021). "Several in vitro studies indicate passive release of HMGB1 by dying cells following subarachnoid haemorrhage, ischaemic stroke, and other non-neurological pathologies." (PMID 33096930, 2020). "They found that HMGB1 is comprehensively expressed in the nuclei of neurons in the control group and significantly reduced after MCAO, and its subcellular translocation is observed at an early stage (12 h) of ischemic stroke." (PMID 31001089, 2019). "The expression levels of TLR2 on monocytes either stimulated with or without HMGB1 were evaluated in ischemic stroke patients." (PMID 31291966, 2019). "It is thought that HMGB1 signals via its presumed receptors, such as toll-like receptors (TLRs), matrix metalloproteinase (MMP) enzymes, and receptor for advanced glycation end products (RAGEs) during ischemic stroke." (PMID 31001089, 2019). "Neutralizing HMGB1 also prevented the negative impact of tibia fracture on ischemic stroke injury, reducing infarct size, behavioral dysfunction and macrophage/microglia infiltration." (PMID 29786644, 2018). "Considering the induction of iNOS, COX-2 has been reported to be involved in the disruption of BBB, our findings suggest that the activation of microglia and cytokine expression contribute to HMGB1-induced BBB disruption and HT development after thrombolysis in ischemic stroke." (PMID 30139371, 2018). "High mobility group box 1 (HMGB1) is non-histone nuclear protein that is currently one of the crucial proinflammatory alarmins in ischemic stroke (IS)." (PMID 29054968, 2017). "Recombinant human thrombomodulin (rhsTM) improves cerebral ischemic injury in mice without hemorrhagic complications through HMGB1 inhibition and has a longer time window to improve the prognosis of ischemic stroke potentially, and its mechanism of action needs to be further investigated." (PMID 38740617, 2025). "In ischemic stroke models, HDAC4 expression is reduced, while HDAC4 may reduce neuronal apoptosis by decreasing high-mobility group box 1 (hMGB1) protein expression and promote angiogenesis and nerve regeneration through the release of VEGF signal of hypoxia-inducible factor-1." (PMID 32963637, 2020). "However, the role of HMGB1 in ischemic stroke may be more complex than this and has not yet been clarified." (PMID 31001089, 2019). "In addition, there is evidence indicating that HMGB1-toll-like receptor 4 (TLR4) signaling participates in neuronal cell death and glutamate neurotoxicity; however, its role in astrocytic dysfunction during ischemic stroke has not been reported before." (PMID 33287126, 2020). "In addition, both groups did not increase the HMGB1 level in plasma, and decreased the number of Iba1 expressing HMGB1 positive cells and TUNEL positive cells, which suggest that CBD may be cerebroprotective not only during the early phase, but also during the chronic phase after ischemic stroke." (PMID 27713349, 2010).
pancreatic cancer (82 papers, 2010 to 2026). "Significant associations between HMGB1 deficiency in tumor cells and unfavorable tumor features have also been previously reported in pancreatic cancer and endometrial cancer." (PMID 40804938, 2025). "From the clinic’s patient data, we further confirmed that HMGB1 is associated with pancreatic-carcinoma TNM staging and metastasis." (PMID 29615080, 2018). "Subsequently, we investigated whether HMGB1 could alleviate the inhibition of ferroptosis caused by METTL3 in pancreatic cancer cells." (PMID 40495163, 2025). "Indeed, HMGB1 is released in the TME after chemotherapy in breast and pancreatic cancer patients, and high HMGB1 levels have been associated with poor response to treatment in pancreatic and triple negative breast cancer patients." (PMID 33321934, 2020). "Also, a high HMGB1 level was significantly associated with poor prognosis in advanced-pancreatic-cancer patients both at baseline and following radiotherapy." (PMID 29615080, 2018). "Next, we determined whether pharmacologic inhibition of nuclear HMGB1 loss and release by glycyrrhizin prevents K-Ras-induced pancreatic cancer initiation under inflammatory conditions." (PMID 28374746, 2017). "In clinical trials involving patients with pancreatic cancer, inhibiting HMGB1 has been shown to enhance sensitivity to chemotherapy." (PMID 41296391, 2025). "We found that METTL3 is highly expressed in pancreatic cancer and regulates ferroptosis and gemcitabine resistance by promoting the degradation of HMGB1 in an m6A-YTHDF2-dependent manner." (PMID 40495163, 2025). "HMGB1 activates the Wnt signaling pathway in pancreatic cancer cells, increases the level of p‐GSK 3β, and thereby influences cell proliferation, migration, and the EMT process." (PMID 41354099, 2025). "Here, we first prove that METTL3 is highly expressed in pancreatic cancer and inhibits ferroptosis-induced gemcitabine resistance, and HMGB1 is identified as a downstream target of METTL3." (PMID 40495163, 2025). "Previous studies suggested that among various cancer types, pancreatic cancer cells release the highest levels of HMGB1 when compared with breast and lung cancers." (PMID 37897664, 2024). "The HMGB1/RAGE axis has been shown to promote autophagy in pancreatic cancer and contribute to its progression in multiple studies." (PMID 38529373, 2024). "In conclusion, lucidone promotes apoptosis in human pancreatic cancer cells through the HMGB1-RAGE axis." (PMID 38529373, 2024). "Inhibition of the HMGB1-RAGE axis leads to reduced autophagy in pancreatic cancer and inhibits its progression." (PMID 38529373, 2024). "Two noteworthy RAGE ligands, namely, S100P and high mobility group box 1 (HMGB1), have undergone extensive examination in the context of pancreatic cancer." (PMID 39087024, 2024). "For this purpose, we calculated Pearson’s correlations between the transcript levels of 13 cancer-related S100 genes and HMGB1 in a cDNA array containing 19 pancreatic cancer tumor samples, and in 8 human pancreatic cancer cell lines." (PMID 37627239, 2023). "It was previously reported that HMGB1 is able to promote tumor progression in prostate cancer and pancreatic cancer and enhance chemoresistance in acute leukemia cells." (PMID 37880798, 2023). "Similar findings were observed when pancreatic tumor cells were treated with free HMGB1 and NET-induced EMT was blocked when anti-HMGB1 thrombomodulin was applied." (PMID 36050539, 2023). "Our data suggest that many S100 proteins crosstalk in pancreatic tumors either with other members of the S100 family, or with HMGB1." (PMID 37627239, 2023). "In recent years, S100 proteins and high mobility group box 1 (HMGB1) were shown to actively participate in multiple aspects of pancreatic cancer." (PMID 37627239, 2023). "In this study, we investigate the possible correlations, at the transcript level, between S100s and HMGB1 in pancreatic cancer." (PMID 37627239, 2023).
pancreatic cancer (continued). "HMGB1-triggered inflammation was associated with the MAPK pathway, and the HMGB1/RAGE/PI3K/Akt pathway was involved in regulating cell proliferation and autophagy in pancreatic cancer." (PMID 35457254, 2022). "In preclinical in vitro and in vivo studies, gemcitabine effectively inhibited tumour growth by inducing immunogenic cell death in pancreatic cancer and increased ATP and HMGB1 release." (PMID 36342599, 2022). "The activation of the RAGE/HMGB1 axis has similar effects on pancreatic cancer cells as the activation of the RAGE/S100P axis." (PMID 33915939, 2021). "In the present study, we show that ANRIL was up-regulated while miR-181a was down-regulated in pancreatic cancer tissues and HMGB1 was highly expressed." (PMID 34374662, 2021). "Taken together, these results indicated that miR-181a has tumor-inhibiting activity in pancreatic cancer cells, and the biological effect of HMGB1 present the opposite effect." (PMID 34374662, 2021). "The results of qRT-PCR and western blot showed that the expression of ANRIL and HMGB1 was obviously higher in pancreatic cancer tissues than that in adjacent tissues." (PMID 34374662, 2021). "The results of CFSE showed that exogenous HMGB1 promotes the proliferation and metastasis of pancreatic cancer cells." (PMID 34805222, 2021). "Irradiated pancreatic cancer cells secrete HMGB1 and engage TLR2 to significantly promote cell migration." (PMID 33922955, 2021). "To examine the effect of ANRIL-miR-181a-HMGB1 axis on gemcitabine chemotherapy for pancreatic cancer, we tested the effects of gemcitabine and the pathway on the proliferation of pancreatic cancer cells." (PMID 34374662, 2021). "The western blot results showed activation of p-GSK 3β and up-regulation of N-CA, Bcl-2, and Ki67 in response to HMGB1 stimulation, while E-CA expression was down-regulated in pancreatic cancer cells in response to HMGB1 stimulation." (PMID 34805222, 2021). "In particular, in pancreatic cancer cells, upon the binding of HMGB1 (High mobility group box1) to TLR2, the PI3K/pAKT pathway is activated with subsequential induction of the epithelial-mesenchymal transition necessary for the metastatic phenotype." (PMID 34884547, 2021). "Oxaliplatin, capable of ICD, increased the expression of CRT, ATP and HMGB1 from pancreatic tumour cell lines, in line with previous studies." (PMID 32661823, 2021). "In conclusion, our data suggest that exogenous HMGB1 promotes the proliferation and metastasis of pancreatic cancer cells after radiotherapy." (PMID 34805222, 2021). "The expression levels of ANRIL and HMGB1 in pancreatic cancer was firstly examined by us, and we collected 5 pairs of pancreatic and precancerous tissues." (PMID 34374662, 2021). "ICD is characterized by calreticulin expression and high‐mobility group box 1 (HMGB1) release in dying Kras‐induced pancreatic cancer (KPC) cells, which is demonstrated in a vaccination experiment to prevent KPC tumor growth on the contralateral site." (PMID 33747719, 2021). "RAGE activation by HMGB1 has been shown to stimulate pancreatic cancer cell proliferation, migration, and tumor growth, while promoting chemoresistance by sustaining autophagy and decreasing apoptosis." (PMID 33915939, 2021). "The two RAGE ligands S100P and HMGB1 have been shown to stimulate RAGE in human pancreatic cancer cells and tumors and to promote pancreatic tumorigenesis." (PMID 33915939, 2021). "We further investigated the biological function of miR-181a and HMGB1 on autophagy of pancreatic cancer cells." (PMID 34374662, 2021). "Two ligands of RAGE, S100P, and high mobility group box 1 (HMGB1), have been extensively studied in the context of pancreatic cancer." (PMID 33086527, 2020). "There was an enhanced inflammatory response in pancreatic tumors and after chemotherapy with a significant increase in extracellular HMGB-1, and stromal infiltration by CD-8+ T-lymphocytes in human PDAC tissue." (PMID 31921387, 2019).
pancreatic cancer (continued). "Several clinical studies have proved that HMGB1 is overexpressed in a variety of human neoplasms, including breast, colorectal, hepatocellular/biliary, lung, and pancreatic cancer." (PMID 30962261, 2019). "Inhibiting the expression and activity of HMGB1 attenuated the dedifferentiation stimulating effect of irradiated, dying cells on C133− pancreatic cancer cells in vitro and in PDX models." (PMID 31558702, 2019). "Our results for the first time supply the direct evidence that dying cells derived HMGB1 induced the CD133− cancer cells dedifferentiation in pancreatic cancer following radiotherapy." (PMID 31558702, 2019). "In this study, we found that dying cells-released HMGB1 promoted pancreatic cancer cells dedifferentiation by decreasing YAP phosphorylation and triggering YAP nuclear translocation." (PMID 31558702, 2019). "To examine the possible role of dying cell derived HMGB1 in dedifferentiation of resident cancer cells, we silenced HMGB1 using two RNAi in primary and established pancreatic cancer cells, and the silencing efficacy was confirmed by western blot." (PMID 31558702, 2019). "We are interested in the mechanistic role of dying cells-derived HMGB1 in CD133− pancreatic cancer cells dedifferentiation following radiotherapy." (PMID 31558702, 2019). "Our previous work confirmed that dying cells derived HMGB1 accelerated pancreatic carcinoma metastasis following radiotherapy." (PMID 31558702, 2019). "Overall, we propose a novel strategy combining HMGB1 inhibitors with irradiation for synergistic pancreatic carcinoma treatment." (PMID 31558702, 2019). "Several reports have also revealed that HMGB1 is involved in the metastatic phenotype of pancreatic cancer." (PMID 29615080, 2018). "HMGB1 gene knockdown attenuated the migration-stimulating effect of irradiated, dying cells on living pancreatic cancer cells." (PMID 29615080, 2018). "The functions of HMGB1 in pancreatic cancer are complicated and paradoxical depending on the intracellular or extracellular locations." (PMID 29615080, 2018). "Our results first demonstrated that dying-cell-derived HMGB1 can induce the pancreatic cancer cells’ EMT program and further promote metastasis." (PMID 29615080, 2018). "We found that inhibiting HMGB1 by down-regulating HMGB1 in irradiated cancer cells or by adding an HMGB1 inhibitor in the supernatant attenuated the pancreatic cancer cell migration." (PMID 29615080, 2018). "A series of experiments were conducted to investigate the role of dying-cell-derived HMGB1 on the invasion of pancreatic cancer in vitro and cancer metastasis in vivo." (PMID 29615080, 2018). "We first examined the release of HMGB1 from the pancreatic cancer cells into the medium after irradiation." (PMID 29615080, 2018). "The serum results showed that the HMGB1 level was higher in pancreatic carcinoma following radiotherapy." (PMID 29615080, 2018). "Our tissue microarray analysis of patients with pancreatic cancer reveals a significant correlation between reduced HMGB1 expression and poor survival." (PMID 28374746, 2017). "A similar stress response was observed in the human PANC-1 pancreatic cancer cell line, as well as using an ELISA to measure HMGB-1 release in both cell types." (PMID 29180759, 2017). "The expression of HMGB1 protein, especially nuclear HMGB1, was decreased in pancreatic tumor compared with adjacent normal pancreatic tissue and normal tissue." (PMID 28374746, 2017). "Among included studies, 4 researches showed that overexpressed serum HMGB1 was closely correlated with the advanced stage of cancer in pancreatic cancer, cervical carcinoma, and malignant pleural mesothelioma." (PMID 27391431, 2016). "The deregulation of the AGER ligand HMGB1 is expressed in many cancer cells including pancreatic cancer cells." (PMID 25197670, 2014).
pancreatic cancer (continued). "HMGB1 has been proposed as mediator of pancreatic tumor cell resistance to antitumoral drugs since interference RNA-mediated silencing of HMGB1 makes PDAC-derived cells more sensitive to the apoptotic cell death induced by melphalan treatment." (PMID 22291707, 2012). "In the current study, TTFields application significantly suppressed c-Myc expression and induced immunogenic cell death (ICD)-characterized by increased calreticulin cell-surface exposure, extracellular ATP secretion, and elevated HMGB1 release-in pancreatic cancer models." (PMID 41760592, 2026). "This suggests that targeting HMGB1 may promote ferroptosis in pancreatic cancer cells while inhibiting GEM resistance and preventing further progression of this disease." (PMID 40495163, 2025). "Similarly, the protein phosphatase PPM1G has been identified as a direct upstream regulator that upregulates HMGB1 expression, thereby promoting both HMGB1-dependent autophagy and progression of pancreatic cancer." (PMID 41465435, 2025). "METTL3 affects pancreatic cancer progression by promoting degradation of HMGB1." (PMID 40495163, 2025). "To investigate whether HMGB1 can regulate the sensitivity of pancreatic cancer cells to gemcitabine, we initially employed autodock vina software for analyzing the free energy between HMGB1 and gemcitabine molecules." (PMID 40495163, 2025). "In addition to the receptor itself, RAGE ligands such as S100P and high mobility group box 1 (HMGB1) have been widely investigated for their roles in pancreatic cancer." (PMID 39796649, 2024). "HMGB1 also plays a key role in the onset and development of pancreatic cancer." (PMID 37897664, 2024). "Inhibition of the HMGB1-RAGE axis in pancreatic cancer cells also induces cell apoptosis." (PMID 38529373, 2024). "These newly observed interdependencies may be used to further the characterization of pancreatic tumors based on S100 and HMGB1 transcription profiles." (PMID 37627239, 2023). "Both in vitro and PDX models showed that inhibiting HMGB1 expression in irradiated, dying cells could attenuate the dedifferentiation stimulation effect on C133- pancreatic cancer cells." (PMID 35812184, 2022). "After treatment with 100ng/ml exogenous HMGB1, the western blot results showed the activation of p-GSK 3β and the up-regulation of N-CA, Bcl-2, and Ki67 in response to HMGB1 stimulation, while E-CA expression was down-regulated in pancreatic cancer cells in response to HMGB1 stimulation." (PMID 34805222, 2021). "However, miR-218 can inhibit the metastatic spread of tumours including non-small cell lung cancer and pancreatic cancer by blocking the expression of HMGB1." (PMID 34445745, 2021). "The second RAGE ligand relevant to pancreatic cancer is HMGB1." (PMID 33915939, 2021). "Previous studies have shown that the HMGB1/RAGE axis promoted autophagy in pancreatic tumors." (PMID 33915939, 2021). "HMGB1 plays a pivotal role in the progression and development of pancreatic cancer." (PMID 34805222, 2021). "The inhibition of ANRIL could restrain the cell proliferation, invasion, migration of pancreatic cancer, and reduce chemotherapy resistance to gemcitabine through sponging miR-181a to target HMGB1-induced cell autophagy." (PMID 34374662, 2021). "Since HMGB1 could reverse the effect of miR-181a on pancreatic cancer cells, we further explored the relationship between them." (PMID 34374662, 2021). "However, additional experiments are necessary to determine if HMGB1 promotes autophagy through its interaction with RAGE in our experimental model of pancreatic cancer." (PMID 33915939, 2021). "This means that inhibiting ANRIL maybe increase the sensitivity of pancreatic cancer cells to chemotherapy through the miR-181a / HMGB1 pathway." (PMID 34374662, 2021). "In pancreatic cancer, it was reported that HMGB1 or its receptor RAGE by RNAi or antisense nucleotide could inhibit cell invasion and augment chemotherapy sensitivity partly by down-regulation of autophagy." (PMID 34933679, 2021).